AHR (aryl hydrocarbon receptor)
Diseases named in the same sentence as AHR in open-access papers (continued):
Sharing a sentence is not in itself a finding about the gene and the disease.
lung carcinoma (continued). "On this background, we discuss the role of AhR and PAHs in lung cancer development caused by air pollution focusing on the tumor promoting properties including metabolism, immune system, cell proliferation and survival, tumor microenvironment, cell-to-cell communication, tumor growth and metastasis." (PMID 37696458, 2023). "In light of the emerging evidence suggesting that lung cancer development from air pollution differs from what is seen in smokers, this review aims to address the many-faceted roles of PAHs and AhR in cancer development associated with combustion particle exposure." (PMID 37696458, 2023). "The role of variants belonging to Wnt/AhR-pathways in lung cancer susceptibility may be underrated in main-effects association analysis." (PMID 35101137, 2022). "Furthermore, a TCGA analysis confirmed that a high score of the AhR-associated genetic signature is associated with poorer survival in bladder, cervical, glioblastoma, pancreatic, head and neck, and lung carcinoma, as well as in melanoma." (PMID 35681770, 2022). "AhR participates through physical association with the nuclear factor kappa-light-chain-enhancer subunits of activated B cells (NF-κB), as well as influences downstream signaling pathways, which are involved in controlling lung cancer initiation and promotion." (PMID 35683027, 2022). "In addition, single-nucleotide polymorphisms (SNPs) in AHR were identified as risk factors for the development of lung cancer in a population of Chinese cigarette smokers; other AHR SNPs were recently associated with higher risk of Crohn's disease." (PMID 33746961, 2021). "Anti-PD-L1 antibody or deficiency in AhR significantly suppresses BaP-induced lung cancer." (PMID 30850589, 2019). "In this study, we demonstrate that PARP7 enzymatic activity coordinates with basal aryl hydrocarbon receptor (AHR) transcriptional activity to mediate homeostasis in lung cancer cells." (PMID 40493189, 2025). "PM2.5 exposure has been linked to various mechanisms that initiate and promote lung cancer, particularly through the actions of EGFR and AhR." (PMID 39578555, 2025). "The upregulation of lymphoid-specific helicase/SMARCA6 activated AHR signaling during lung cancer progression." (PMID 40765830, 2025). "Research on breast and lung cancers has highlighted the kynurenine–aryl hydrocarbon receptor (AhR) axis and serotonin signaling as critical pathways contributing to tumor progression and immune evasion." (PMID 40666095, 2025). "They deepen the understanding of smoking’s impact on the trajectory towards lung cancer, spotlighting the diverse roles of AHR in this disease’s development." (PMID 40823246, 2025). "To assess AHR expression in human lung cancers, we analyzed data from the publicly available TCGA lung cancer dataset." (PMID 40303305, 2025). "The cumulative effects of PM2.5 exposure, including ROS generation, inflammation, DNA damage, and activation of oncogenic pathways like EGFR and AhR, create a vicious cycle that promotes lung cancer development and progression." (PMID 39578555, 2025). "AhR expression is higher in lung cancer tissues than in normal tissues, indicating that AhR has a tumor-suppressive role in carcinogenesis." (PMID 38680496, 2024). "Accordingly, AhR inhibition with α-naphthoflavone (ANF) significantly enhances the efficacy of α-PD-L1 in lung cancer mouse models and prolongs the lifespan of mice." (PMID 38807762, 2024). "Chemical carcinogenesis that pivots on the AHR pathway appears to be the bridge linking the development and progression of breast and lung cancers." (PMID 38982523, 2024). "Collectively, these results suggest that AhR mediates BaP-induced PD-L2 expression in lung cancer cells." (PMID 39042313, 2024). "The aromatic hydrocarbon receptor (AHR), a ligand-dependent transcription factor, is known for its role in lung cancer induced by cigarette smoking." (PMID 38549355, 2024).
lung carcinoma (continued). "Understanding the role of the AhR/AhRR/CYP1A1 axis in lung cancer progression is of importance to improve current therapeutic approaches and develop new therapeutic strategies for the treatment of NSCLC." (PMID 39199657, 2024). "Overactivation by treatment with the AhR agonist TCDD led to increased cellular proliferation in a lung cancer cell line, and a similar trend was seen in human mammary epithelial cells." (PMID 38339226, 2024). "An increasingly visible role for AhR as a regulator of lung cancer tumorigenicity is being appreciated, with most reports focused on non-small cell lung cancers." (PMID 38807762, 2024). "A solid body of data published by various laboratories supports a pro-tumorigenic role for AhR in lung cancer." (PMID 38807762, 2024). "For lung cancer, immunohistochemistry studies on human tissue samples revealed that normal human lung tissues expressed high levels of AhR." (PMID 38518996, 2024). "In contrast, AhR expression was much lower in the lung cancer tissues, including samples of lung squamous cell carcinoma, lung adenocarcinoma and invasive lung cancer." (PMID 38518996, 2024). "While these studies provide evidence that AhR acts as a tumor promoter, there are also reports suggesting a tumor suppressive function for AhR in lung cancer." (PMID 38807762, 2024). "The tumor suppressor-like property of AHR by repressing TGFβ signaling was most recently elucidated in the anti-metastasis of AHR in human lung cancer cells." (PMID 37151890, 2023). "It is, however, important to consider that the role of AhR in lung cancer development is highly complex and, as is often the case in AhR research, that contrasting findings have been reported." (PMID 37696458, 2023). "Aryl hydrocarbon receptor (AHR), an important transcription factor, is involved in the initiation and progression of lung cancer." (PMID 37988371, 2023). "Accordingly, the data from this study suggest that AHR has tumor suppressor-like activity for human lung cancer, and one of the carcinogenic mechanisms of arsenic is likely mediated by the inhibition of arsenic on the tumor suppressor-like activity of AHR." (PMID 37151890, 2023). "To evaluate the role of TMPRSS2 expression in lung cancer progression in vivo, we examined the expression levels of TMPRSS2, IL18, and nuclear AhR by IHC in tumor specimens from 25 lung cancer patients." (PMID 36975376, 2023). "Collectively, these findings point towards a potential role of AhR in air pollution-mediated lung ADCs with EGFR driven mutations and lung cancer." (PMID 37696458, 2023). "Benzo(a)pyrene is a ubiquitously present environmental contaminant that induces lung cancer after being converted into active metabolites via aryl hydrocarbon receptor (AhR)-mediated metabolic activation." (PMID 36765542, 2023). "The expression levels of TMPRSS2 were found to correlate with nuclear AhR expression and with cancer stage in lung cancer patient tissue." (PMID 36975376, 2023). "As discussed in this review, the role of AhR in lung cancer development extends far beyond the regulation of PAH metabolism, adduct formation, and genotoxicity." (PMID 37696458, 2023). "The less abundant expression of AHR and lack of survival evidence in SCLC patients led to our less focus on this lung cancer subtype, and we then investigated the significance of AHR and PLK1 in other two lung cancer subtypes." (PMID 37988371, 2023). "We studied two important proteins in lung cancer: aryl hydrocarbon receptor (AHR) and Polo-like kinase 1 (PLK1), which are known to worsen many types of cancer." (PMID 37988371, 2023). "The tumor suppressor-like feature of AHR was additionally substantiated by the diminished expression of AHR in human lung cancer tissues and poorer prognosis of the patients with lower AHR tumors." (PMID 37151890, 2023).
lung carcinoma (continued). "Alongside its intricate associations with AHR and PLK1, a comprehensive exploration of these multifaceted aspects promises to enhance our comprehension of lung cancer etiology, ultimately translating into improved clinical care for patients." (PMID 37988371, 2023). "For that purpose, we examined AHR expression in human lung cancer tissue samples along with normal lung tissues by immunohistochemistry (IHC)." (PMID 37151890, 2023). "Of note, although AhR contributes to cigarette smoke- and environmental pollutant-induced lung damage, recent studies have indicated that AhR negatively regulates the progression of lung cancer." (PMID 35656117, 2022). "A large number of studies had discussed the association of the genetic polymorphism of AHR, ARNT, AHRR genes and human diseases such as Crohn’s disease (CD), lung cancer, male infertility, and autoimmune diseases." (PMID 35309329, 2022). "Polycyclic aromatic hydrocarbon (PAH) exposure is known to promote lung cancer development via AhR signalling." (PMID 36355934, 2022). "Previous studies have identified that increased AhR activity augments cell migration in lung cancer and gastric cancer via a mechanism involving JNK activation." (PMID 35773697, 2022). "Through AhR signalling, polycyclic aromatic hydrocarbon exposure increases the genesis and progression of lung cancer." (PMID 36355934, 2022). "For example, ABT-263 (Navitoclax), which targets the apoptosis inhibitor Bcl-2, was more effective in lung-cancer cell lines that weakly express AhR." (PMID 33451095, 2021). "In vitro experiments also confirmed that BNIP3 participated in lung cancer cell migration by interacting with aryl hydrocarbon receptor (AhR)." (PMID 31938577, 2020). "It was reported that AhR is overexpressed in some cancers including lung carcinoma, gastric carcinoma and medulloblastoma and an oncogenic potential of AhR was reported in hepatocarcinoma and stomach tumour." (PMID 31659416, 2020). "Intriguingly, AHR is a sensor and regulator of the endogenous defense system against xenobiotic chemicals which are implied in lung cancer carcinogenesis and progression." (PMID 33214553, 2020). "Our findings suggest that modulation of AHR activity is a promising strategy to interfere with metastatic progression of lung cancer." (PMID 33214553, 2020). "In an orthotopic, spontaneously metastasizing lung cancer model, we here uncovered AHR-mediated regulation of several metastatic programs including EMT and MMP activity." (PMID 33214553, 2020). "We identified aryl hydrocarbon receptor (AHR), a sensor of xenobiotic chemicals and transcription factor, as suppressor of lung cancer metastasis." (PMID 33214553, 2020). "Established lung cancers with suppressed AHR-dependent defense systems exhibit higher likelihood of metastasis and relapse in murine models and in patients." (PMID 33214553, 2020). "With this in vivo model we undertook an unbiased functional genomics screen and identified aryl hydrocarbon receptor (AHR) as suppressor of metastatic spread in EGFR-driven lung cancer." (PMID 33214553, 2020). "Knockdown of endogenous AHR induces epithelial–mesenchymal transition signatures, increases invasiveness of lung cancer cells in vitro and metastasis formation in vivo." (PMID 33214553, 2020). "Suppression of endogenous AHR increased the metabolic stress resistance of lung cancer models, thus complementing invasiveness in a metastatic phenotype." (PMID 33214553, 2020). "In lung cancer, in vitro studies indicated that AHR overexpression negatively regulates tumorigenesis by reducing lung cancer cell viability, growth and invasive capacity." (PMID 33214553, 2020). "In summary, our findings strongly support a role of AHR as relevant suppressor of lung cancer metastasis." (PMID 33214553, 2020). "In conclusion, UCHL3 is an AhR DUB that promotes lung cancer proliferation, tumor growth and tumor stem-like properties through stabilizing AhR by its deubiquitination." (PMID 32546741, 2020).
lung carcinoma (continued). "We observed that both AhR and UCHL3 protein levels were increased in lung cancer tissues compared with normal tissues, and a positive correlation between AhR and UCHL3 protein levels was observed." (PMID 32546741, 2020). "AHR expression is correlated with smoke-induced lung cancer and is believed to contribute to lung cancer initiation." (PMID 31416966, 2019). "We found that in AhR+/+ mice, BaP induced lung cancer; but in AhR-/- mice, BaP-induced lung cancer was inhibited, life span was prolonged, and PD-L1 upregulation was markedly attenuated." (PMID 30850589, 2019). "AhR inhibitors exert significant antitumor activity and synergize with anti-PD-L1 antibody in lung cancer mouse models." (PMID 30850589, 2019). "The role of the AhR in the promotion of lung cancer pathogenesis was recently reviewed, therefore it will only be briefly discussed here." (PMID 30563036, 2018). "For example, over-expression of the AhR occurs in many types of human cancers, including lung, breast and gastric cancers and there is recent evidence supporting a pro-oncogenic role for AhR over-expression in lung cancer." (PMID 30563036, 2018). "In lung cancer cells, AhR-RelA dimers bind to a DRE-independent NF-κB response element in the IL-6 promoter, resulting in increased IL-6 expression." (PMID 30563036, 2018). "We sought to elucidate the exact signalling pathway involved in AhR-regulated autophagy and EMT, particularly the novel crosstalk to determine how AhR levels affect lung cancer metastasis." (PMID 28195146, 2017). "In summary, this is the first study of AhR-regulated autophagy in lung cancer EMT, which is dependent on the role of cellular autophagy in cancer metastasis and endogenous AhR functions." (PMID 28195146, 2017). "In this study, we found that AhR protein expression altered EMT via cell autophagy in different lung cancer cells and that high endogenous AhR expression contributed to downregulation of cell autophagy and EMT inhibition." (PMID 28195146, 2017). "Among these regulatory factors, we identify AHR, the aryl hydrocarbon-receptor which controls a healthy immune response in the lung epithelium and whose repressor, AHRR, has recently been implicated in smoking-mediated lung cancer." (PMID 29262847, 2017). "The genetic polymorphisms in AHRR have been shown to be risk factors for cancer via ameliorating this AhR repressor activity, and DNA methylation change in AHRR has been linked to smoking exposure and lung cancer." (PMID 28056099, 2017). "Analysis of AHR-expression levels in non-small cell lung cancer cell lines and lung cancer tissues revealed an inverse correlation between AHR protein levels and tumor cell invasion and metastasis." (PMID 27752740, 2017). "Additionally, the expression of PD-L1 in lung epithelial cells is induced by AHR and, in lung cancer, AHR expression and nuclear localization are positively correlated with response to the anti–PD-1 antibody pembrolizumab." (PMID 41295982, 2026). "To further explore AHR's prognostic value in lung cancer, we conducted survival analyses." (PMID 40303305, 2025). "Together, these findings suggest that increased AHR expression correlates with favorable outcomes in lung cancer and may serve as a beneficial prognostic factor in aggressive cases." (PMID 40303305, 2025). "Given AHR's previously demonstrated tumor-suppressive role in lung cancer 17, TOX upregulation may contribute to As3+-induced malignancy." (PMID 40303305, 2025). "We further examined AHR expression across different lung cancer subtypes and metastatic tissues." (PMID 40303305, 2025). "The Trp metabolite D‐Kyn induces EMT in lung cancer through AhR activation." (PMID 41332472, 2025). "Furthermore, AhR activation maintains non‐small cell lung cancer stem cells via the Jak2/STAT3 signaling pathway." (PMID 41332472, 2025).
lung carcinoma (continued). "However, this study revealed an important role of AHR in being the bridge linking the development and progression of breast and lung cancers as it is involved (directly and or indirectly) in the regulation of biological pathways mapped out in this study." (PMID 38982523, 2024). "Thus, the role of AhR in lung cancer requires further study to fully understand its tumorigenic functions." (PMID 38807762, 2024). "The function of AhR in lung cancer has been recently reviewed." (PMID 38518996, 2024). "Although evidence suggests that targeting AhR may help prevent and treat lung cancer, other studies indicate that AhR can act as a repressor of oncogenic signaling." (PMID 38518996, 2024). "In lung cancer cells, cells overexpressing AhR exhibited lower cell mobility, high expression of E-cadherin and low expression of waveform proteins (biomarkers associated with EMT), suggesting that higher AhR expression are associated with lower cell motility." (PMID 38434684, 2024). "For instance, overexpression of PD‐L1 induced by the aryl hydrocarbon receptor in non–small cell lung cancer reduces the efficacy of anti‐PD‐1 treatment; IL‐17A increases PD‐L1 expression via the p65/NRF1/miR‐15b‐5p axis, promoting resistance of CRC to PD‐1 antibody therapy." (PMID 39503247, 2024). "In contrast, the AHR expression was diminished in the lung cancer tissues." (PMID 37151890, 2023). "PM2.5 promotes lung cancer progression through activation of the AhR‐TMPRSS2‐IL18." (PMID 36975376, 2023). "In conclusion, carvedilol prevents B(a)P-induced lung toxicity, inflammation and carcinogenesis via targeting multiple oncogenic signaling pathways, including MAPK, AhR and NF-κB, and, therefore, represents a promising drug candidate for use in lung cancer chemoprevention." (PMID 36765542, 2023). "AHR has been shown to account for lung cancer carcinogenesis." (PMID 37988371, 2023). "Loss of p27Kip1 in lung cancer cells resulted in significantly enhanced basal and ligand-induced levels of AhR target genes such as CYP1A1 and AHRR, and this negative regulation was found for the transcription of p27Kip1 itself." (PMID 37106727, 2023). "Additionally, the results are inconsistent, with several reports indicating AhR downregulation in lung cancer 50, but others reported AhR overexpressed 51, 52, consistent with our findings." (PMID 37056388, 2023). "Thus, the angiogenic VEGF-signal appears to arise from activation of AhR in both immune cells and cancer cells, which in the case of lung cancer would be bronchial and alveolar epithelial cells." (PMID 37696458, 2023). "The AHR pathway is a sensor and regulator of the defence system against xenobiotic chemicals and is also linked with TGF-β signalling to downregulate SMAD4 and impair invasive capacity and activate autophagy in lung cancers." (PMID 36826068, 2023). "Collectively this suggests that the role of the mitochondrial pool of AhR in lung cancer could be worth exploring." (PMID 37696458, 2023). "Notably, we found that the benzimidazoisoquinoline 11-Cl-BBQ drove potent AhR-dependent antiproliferative effects in lung cancer cells." (PMID 37106727, 2023). "We measured AhR protein expression levels in different lung cancer cell lines." (PMID 37056388, 2023). "A role of AhR in suppressing lung cancer cell metastasis and migration has also been elucidated." (PMID 37106727, 2023). "On the other hand, AhR expression has been reported to suppress lung cancer metastasis after orthotopic implantation of human adenocarcinoma cell lines (H1975, A549 and H1299) in SCID CB.17 mice, suggesting that AhR suppresses lung carcinogenesis irrespective of the dominant oncogenic driver." (PMID 37696458, 2023). "Although both PLK1 and AHR are closely related to lung cancer tumorigenesis, whether they cooperate to accelerate tumor progression remains unknown." (PMID 37988371, 2023).